BMPR1A (bone morphogenetic protein receptor type 1A)
Description:
On ligand binding, forms a receptor complex consisting of two type II and two type I transmembrane serine/threonine kinases. Type II receptors phosphorylate and activate type I receptors which autophosphorylate, then bind and activate SMAD transcriptional regulators. Receptor for BMP2, BMP4, GDF5 and GDF6. Positively regulates chondrocyte differentiation through GDF5 interaction. Mediates induction of adipogenesis by GDF6. May promote the expression of HAMP, potentially via its interaction with BMP2 (By similarity).
Synonyms: BMPR-1A; ALK-3; SKR5; CD292; ACVRLK3; ALK3; 10q23del
Tractability: Small molecule: a high-quality ligand is known; it belongs to a druggable protein family. Antibody: UniProt places it where antibodies can reach, with high confidence; its Gene Ontology location is reachable by antibodies, with high confidence; UniProt predicts a signal peptide or a membrane-spanning region. PROTAC: it is named in the literature on targeted protein degradation; ubiquitination databases record sites on it; a small molecule that binds it is known. Other modalities: an approved drug acts on it.
Target class: Enzyme; TKL protein kinase group; TKL protein kinase STKR family; TKL protein kinase STKR Type 1 subfamily; Protein Kinase; Kinase
Gene: Protein-coding gene on chromosome 10 (86,755,763 to 86,932,825, forward strand). Ensembl gene ENSG00000107779.
Subcellular location: Cell membrane; Cell surface
Subcellular location (Human Protein Atlas): Cytosol
Pathways (Reactome):
Signal Transduction: Signaling by BMP
Gene Ontology:
Molecular function: ATP binding; BMP binding; BMP receptor activity; protein binding; protein homodimerization activity; protein serine/threonine kinase activity; SMAD binding; transforming growth factor beta receptor activity, type I; transmembrane receptor protein serine/threonine kinase activity; protein kinase activity
Biological process: angiogenesis; anti-Mullerian hormone receptor signaling pathway; BMP signaling pathway; cellular response to BMP stimulus; immune response; negative regulation of smooth muscle cell migration; positive regulation of bone mineralization; positive regulation of gene expression; positive regulation of osteoblast differentiation; positive regulation of SMAD protein signal transduction; positive regulation of transcription by RNA polymerase II; positive regulation of vascular associated smooth muscle cell proliferation; transforming growth factor beta receptor signaling pathway; atrioventricular node cell development; atrioventricular valve development; cardiac conduction system development; cardiac right ventricle morphogenesis; cell differentiation; cellular response to growth factor stimulus; dorsal aorta morphogenesis; dorsal/ventral pattern formation; embryonic organ development; endocardial cushion formation; endocardial cushion morphogenesis; fibrous ring of heart morphogenesis; and 21 more
Cellular component: caveola; external side of plasma membrane; plasma membrane; cell surface; HFE-transferrin receptor complex; membrane; receptor complex; dendrite; neuronal cell body
Genetic constraint (gnomAD): Loss-of-function variants: 7 observed, 67.28 expected, observed/expected ratio (o/e) 0.1, 90% interval 0.058 to 0.19. The upper end of that interval is the gene's LOEUF score, 0.19, which puts it in group 1 of 6, group 1 being the genes least tolerant of losing a copy. Missense variants: 408 observed, 688.81 expected, observed/expected ratio (o/e) 0.59, 90% interval 0.55 to 0.64. Synonymous variants: 200 observed, 233.77 expected, observed/expected ratio (o/e) 0.86, 90% interval 0.76 to 0.96.
Gene-disease validity (ClinGen):
ClinGen rates the evidence that BMPR1A causes each of these diseases.
juvenile polyposis syndrome (autosomal dominant): Definitive. Juvenile gastrointestinal polyposis (JIP) is a rare condition characterized by the presence of juvenile hamartomatous polyps in the gastrointestinal (GI) tract.
pulmonary arterial hypertension (inheritance undetermined): Disputed. Pulmonary arterial hypertension (PAH) is a group of diseases characterized by mean pulmonary artery pressure >20 mmHg and elevated pulmonary arterial resistance leading to right heart failure.
Cancer hallmarks: invasion and metastasis (promotes)
Homologues: Orthologues: chimpanzee BMPR1A (99% identical), macaque BMPR1A (99% identical), dog BMPR1A (99% identical), pig BMPR1A (99% identical), mouse Bmpr1a (98% identical), rat Bmpr1a (97% identical), rabbit BMPR1A (96% identical), guinea pig BMPR1A (95% identical), tropical clawed frog bmpr1a (80% identical), zebrafish bmpr1ab (75% identical), zebrafish bmpr1aa (75% identical). Paralogues in human: BMPR1B (68% identical), TGFBR1 (47% identical), ACVR1B (46% identical), ACVR1C (45% identical), ACVR1 (44% identical), ACVRL1 (42% identical), ACVR2A (29% identical), ACVR2B (26% identical), TGFBR2 (26% identical), BMPR2 (25% identical), AMHR2 (24% identical).
Diseases named in the same sentence as BMPR1A in open-access papers:
BMPR1A is named in the same sentence as 166 diseases in open-access papers, as found by Europe PMC text mining. Sharing a sentence is not in itself a finding about the gene and the disease. The quoted sentences say what the papers report.
juvenile polyposis syndrome (72 papers, 2004 to 2025). "More than one-third of juvenile polyposis syndrome cases arise from de novo mutations and frequently mutated genes include Bone Morphogenetic Protein Receptor 1A (BMPR1A) or Suppressor Mothers Against Decapentaplegic Homolog 4 (SMAD4 or DPC4)." (PMID 39057027, 2024). "Juvenile polyposis syndrome (JPS) is an autosomal dominant condition associated GPVs in SMAD4 or BMPR1A." (PMID 37258796, 2023). "It is well known that germline mutations in MADH4 or BMPR1A (encoding Smad4 or ALK3, respectively) are present in a large number of patients with juvenile polyposis syndrome." (PMID 35693928, 2022). "Juvenile polyposis (JP) is a rare disease known to be associated with mutations either in SMAD4/BMPR1A." (PMID 35928693, 2022). "Juvenile polyposis of infancy is a very rare condition and is caused by deletions of the BMPR1A and PTEN genes." (PMID 35187600, 2022). "Germline mutations in SMAD4 and BMPR1A genes have been identified to cause juvenile polyposis syndrome (JPS)." (PMID 35320498, 2022). "Alteration in BMPR1A have been strongly associated to an increased susceptibility to the juvenile polyposis syndrome and to colorectal cancer." (PMID 33821390, 2021). "Here we report a de novo germline missense variant in BMPR1A gene in a family with juvenile polyposis." (PMID 33032550, 2020). "Germline genetic testing revealed a de novo germline missense variant in BMPR1A gene in a family with juvenile polyposis." (PMID 33032550, 2020). "Here, we report a germline heterozygous missense variant (c.299G > A) in exon 3 BMPR1A gene in a family with juvenile polyposis." (PMID 33032550, 2020). "Diseases associated with the protein coding gene BMPR1A include juvenile polyposis syndrome and polyposis syndrome, and this gene has been shown to be related to the mammalian target of rapamycin (mTOR) and PI3K/AKT signaling pathways." (PMID 31998776, 2020). "BMPR1A (Bone Morphogenetic Protein Receptor Type 1A) is a cancer predisposing gene, related to polyposis, e.g. Juvenile polyposis syndrome (MIM:174900, MalaCards ID:JVN014), an autosomal dominant GI cancer." (PMID 31888639, 2019). "To study somatic mutation in Drosophila, we generated inducible alleles that mimic human Juvenile polyposis-associated BMPR1A mutations." (PMID 29745898, 2018). "Mutations in BMPR1A have been found in an extended phenotypic spectrum beyond juvenile polyposis, including HMPS, AFAP simplex, familial colorectal cancer type X (FCCX) and early onset CRC without familial history and MSI negative tumours." (PMID 27696107, 2017). "Loss of BMPR1A has previously been associated with the formation of juvenile polyposis, a predisposing factor for gastrointestinal and colorectal cancers." (PMID 27114889, 2016). "Inactivation of Bmpr1a in skin can induce the formation of tumors in hair follicles, and epithelial ablation of Bmpr1a correlates with the occurrence of juvenile polyposis with a risk for colon cancer." (PMID 24731097, 2014). "Mutations in Bmpr1a in the human and mouse are responsible for organ pathogenesis with abnormal cell proliferation, such as juvenile polyposis syndrome and skin tumorigenesis (50, –, 52)." (PMID 24731097, 2014). "Somatic mutations were found in the intracellular kinase domain of bone morphogenetic protein receptor 1A, BMPR1A, of which germline mutations are associated with juvenile polyposis syndrome." (PMID 23497483, 2013). "Another important hereditary condition is the juvenile polyposis syndrome (JPS) which is inherited as an autosomal dominant due to specific mutation in the BMPR1A gene or the SMAD4 gene." (PMID 23737765, 2013).
juvenile polyposis syndrome (continued). "Juvenile polyposis syndrome, an inherited syndrome with high risk of colorectal cancer, is caused by germline mutation of BMPR1A or SMAD4, and importance of BMP signal is supported by its mouse model with transgenic Nog expression or with Bmpr1a inactivation." (PMID 22072987, 2011). "Further functional characterizations identified recurrent somatic mutations in BMPR1A, a protein which has been associated so far with juvenile polyposis syndrome, a cancer predisposition syndrome." (PMID 21203531, 2010). "Humans that are heterozygous for loss-of-function mutations in BMPR1A are known to be at risk for juvenile polyposis, but the risk of osteoarthritis for these people has not been reported." (PMID 15492776, 2004). "Variants in the BMPR1A gene have been associated with juvenile polyposis syndrome." (PMID 40458721, 2025). "SMAD4 and BMPR1A are reported to be associated with Juvenile Polyposis Syndrome." (PMID 38898990, 2024). "BMPR1A variants can cause juvenile intestinal polyposis (MIM #174900)." (PMID 30809968, 2019). "Interestingly, patients with germline mutations in BMPR1a develop Juvenile Polyposis Syndrome, which is characterized by the development of hamartomas and mice with targeted deletion of BMPR1a in skin develop similar hamartomatous lesions." (PMID 26274893, 2015). "Other rare colonic polyposis syndromes for which the genetic basis is known include Cowden syndrome (mutations in PTEN), juvenile polyposis (mutations in SMAD4 or BMPR1A), hereditary mixed polyposis syndrome (mutation in GREM1), and MUTYH-associated polyposis (biallelic mutations in MUTYH)." (PMID 23805267, 2013). "In both CRCs, MSI and MSS, we found somatic mutations in the intracellular kinase domain of bone morphogenetic protein receptor 1A, BMPR1A, a gene where so far germline mutations are associated with juvenile polyposis syndrome, and show that the mutations functionally impair the protein function." (PMID 21203531, 2010). "Germline BMPR1A mutations predispose to juvenile polyposis syndrome; however, our findings indicate that also somatic mutations might play an important role in sporadic colorectal cancer development." (PMID 21203531, 2010). "Pathogenic variants of the bone morphogenetic protein receptor type 1 A (BMPR1A) gene underlie juvenile polyposis syndrome (JPS), a rare autosomal dominant condition characterized by multiple gastrointestinal hamartomatous polyps." (PMID 41023686, 2025). "Hereditary hamartomatous syndromes include Peutz–Jeghers syndrome (PJS, with mutations in LKB1/STK11), PTEN-hamartoma tumor syndrome (PHTS, with mutations in PTEN), and juvenile polyposis syndrome (JPS, with mutations in BMPR1A or SMAD4)." (PMID 38672634, 2024). "Juvenile polyposis syndrome (JPS) is also an inherited autosomal dominant syndrome driven by mutations in either BMPR1A (MIM: 601299) or SMAD4 (MIM: 600993)." (PMID 36551963, 2022). "The SMAD4 germline variant is the most frequently recognized in juvenile polyposis syndrome (JPS), along with the BMPR1A germline variant." (PMID 34476650, 2021). "Individuals with juvenile polyposis syndrome (JPS) are carriers of mutations in crucial components of the BMP pathway such as the BMP receptor 1a (BMPR1a) or the downstream signaling molecule SMAD4." (PMID 32486027, 2020). "Juvenile polyposis syndrome (JPS) belongs to the autosomal dominant hamartomatous polyposis syndromes involving variants in the SMAD4 and BMPR1A genes." (PMID 41226105, 2025). "Mutations in Bone Morphogenetic Protein (BMP) Receptor (BMPR)1A and SMAD4 are detected in 50% of juvenile polyposis syndrome (JPS) patients, who develop stroma-rich hamartomatous polyps." (PMID 36326956, 2023). "When analyzing large rearrangements, we found several cases in which the deletion also affected other genes, such as KLLN, a neighbor gene of PTEN, but also BMPR1A, a further upstream gene associated with juvenile polyposis syndrome (JPS; MIM 174,900) and colorectal cancer risk." (PMID 35227301, 2022).
juvenile polyposis syndrome (continued). "Syndromes and corresponding genes include: SMAD4 (DPC4) and BMPR1A for juvenile polyposis (JPS), STK11 for Peutz–Jeghers (PJS) and PTEN and AKT1 for PTEN hamartomatous syndromes (PHS)." (PMID 36011318, 2022). "Context: Chromosome 10q23 Deletion Syndrome is a rare entity defined by a germline chromosomal deletion that encompasses PTEN and BMPR1A genes associated with PTEN Hamartoma Tumor Syndrome (PHTS) and Juvenile Polyposis Syndrome (JPS), respectively." (PMID 33530161, 2021). "Juvenile polyposis syndrome (JPS) is a rare disorder characterized by the presence of multiple juvenile polyps in the gastrointestinal tract, and germline mutations in SMAD4 or BMPR1A." (PMID 32487124, 2020). "The 2 patients with PHTS and BMPR1A deletions upstream of their individual PTEN deletion had juvenile polyposis, as is often observed in chromosome 10q23 microdeletions involving both genes (OMIM 612242)." (PMID 32003824, 2020). "Some patients have a family history of juvenile polyposis with an autosomal dominant pattern of inheritance, and SMAD4 and BMPR1A have recently been identified as causative genes for juvenile polyposis." (PMID 30043121, 2018). "Mutations in two different genes (BMPR1A and SMAD4) are known to cause juvenile polyposis syndrome in 20% of cases each." (PMID 18826596, 2008). "Hereditary polyposis syndromes (HPS) including familial adenomatous polyposis (FAP), juvenile polyposis syndrome (JPS), and Peutz-Jeghers syndrome (PJS) are all predisposing conditions to colorectal cancer, with a genetic basis (mutations in SMAD4 or BMPR1A genes)." (PMID 41258467, 2025). "These include APC for familial adenomatous polyposis (FAP); BMPR1A and SMAD4 for Juvenile Polyposis Syndrome (JPS); MUTYH for MUTYH-associated polyposis; PTEN for PTEN tumor/hamartoma syndrome (or Cowden syndrome/Bannayan–Riley–Ruvalcaba syndrome); and STK11 for Peutz–Jeghers syndrome." (PMID 37965459, 2023). "In juvenile polyposis, the ESGE and BSG suggest that oesophagogastroduodenoscopy surveillance starts for asymptomatic individuals with SMAD4 mutation at the age of 18, and with BMPR1A mutation at the age of 25 years." (PMID 34944861, 2021). "Recent investigations reported SMAD4 and BMPR1A as genes responsible for juvenile polyposis." (PMID 30043121, 2018). "In addition, inactivation of BMP receptor 1a (BMPR1A) or Mothers against decapentaplegic homolog 4 (SMAD4) results into human juvenile polyposis syndrome (JPS)." (PMID 28159860, 2017). "In the Bmpr1a deletion mice after 1.5 months, the intestine was enlarged in size, with dilated crypts, proliferative villus epithelium invaginations and moderately expanded stromal tissue, resembling the early phenotypes in juvenile polyposis syndrome." (PMID 28059064, 2017). "Additionally, the Hamartomatous polyposis syndromes that englobe the syndrome of PeutzJeghers (PJS), the syndrome of Juvenile Polyposis (JPS), and the syndrome of Cowden are autosomal dominant syndromes caused by germline mutations in STK11/LKB1, BMPR1A/SMAD4, and PTEN, respectively." (PMID 34326875, 2021). "For instance, in Juvenile polyposis syndrome (JPS, MIM: 174900), an autosomal dominant inherited disorder, mutations in BMPR1A have been associated with the development of gastrointestinal cancers." (PMID 30246251, 2019).
juvenile polyposis syndrome (continued). "In contrast, patients with a deletion of the BMPR1A and PTEN gene show a severe clinical picture of juvenile polyposis of infancy and need early gastrointestinal diagnostics and treatment." (PMID 35187600, 2022). "Similarly, germline mutations of bone morphogenetic protein receptor type IA (BMPR1A), a key receptor in the BMP/SMAD signaling pathway, are a cause of juvenile polyposis syndrome (JPS)." (PMID 33822054, 2021). "Cis target gene analysis identified BMPR1A, an important gene for a GIT disease (juvenile polyposis syndrome) in humans, as a candidate cis target gene for lncRNAs in both tissues." (PMID 29510583, 2018). "In the present case, the patient had no family history of juvenile polyposis, and refused a test for germline mutations in the SMAD4 and BMPR1A genes but was diagnosed with JPST based on physical findings and histopathological features." (PMID 35841758, 2022). "Since we found significant cancer-related pathways associated only with BMPR1A but not with WDTC1 or EHD3, and in addition germline mutations in BMPR1A are a known risk factor for juvenile polyposis syndrome, we chose BMPR1A for additional functional assays." (PMID 21203531, 2010).